HIF1A (hypoxia inducible factor 1 subunit alpha)
Diseases named in the same sentence as HIF1A in open-access papers (continued):
Sharing a sentence is not in itself a finding about the gene and the disease.
gallbladder cancer (15 papers, 2014 to 2025). "From these experiments, it is found that the abnormal activation of the HIF-1α/MMPs signaling pathway is an important cause of the proliferation and metastasis of gallbladder cancer." (PMID 40563539, 2025). "In gallbladder cancer, IL-37 was reported to suppress migration and invasion by inhibiting HIF-1α-induced epithelial–mesenchymal transition." (PMID 40444012, 2025). "In particular, miR-143-5p inhibits cell proliferation, migration and invasion in gallbladder cancer targeting HIF-1α, ultimately preventing the epithelial-to-mesenchymal transition." (PMID 31435512, 2018). "linc00152 also utilises HIF-1α to promote EMT in the metastasis of gallbladder cancer, by acting as a ceRNA for miR-138 resulting in the upregulation of HIF-1α, and subsequent progression of EMT." (PMID 28430163, 2017). "In brief, the results of this work suggest that cordycepin down-regulates MDR/HIF-1α through regulating AMPK/mTORC1 signaling in GBC-SD gallbladder cancer cells." (PMID 25046749, 2014). "Since TrkB is highly expressed in gallbladder cancer patients, TrkB or HIF-1α may be promising therapeutic targets." (PMID 40563539, 2025). "Indeed, a recent study found that metformin treatment results in a reduction of HIF1-α protein in human gall-bladder cancer GBC-SD cells." (PMID 34548527, 2021). "We found that cordycepin inhibited mTOR complex 1 (mTORC1) activation and down-regulated multiple drug resistant (MDR)/hypoxia-inducible factor 1α (HIF-1α) expression through activating of AMP-activated protein kinase (AMPK) signaling in gallbladder cancer GBC-SD cells." (PMID 25046749, 2014). "HIF-1α is over-expressed in gallbladder cancer, which is correlated with the poor prognosis." (PMID 25046749, 2014). "Moreover, HIF-1α can also regulate the expression of MMP9 in gallbladder cancer." (PMID 40563539, 2025). "Several studies demonstrated that metformin is able to inhibit the HIF1A signaling pathway in vitro, leading to increased cell death in OCSCC and gallbladder carcinoma." (PMID 40468055, 2025). "HIF-1α signalling was also shown to be involved in drug resistance in multiple cancer types, including RCC, gastric, pancreatic, and gall bladder cancers." (PMID 37296922, 2023). "For example, LINC00152 positively modulates HIF-1a by binding miR-138 to promote metastasis and EMT in gallbladder cancer." (PMID 34168678, 2021). "We present evidence that AMPK activation by cordycepin induces mTORC1 in-activation and hypoxia-inducible factor 1α (HIF-1α)/multiple drug resistant (MDR) degradation, which mediates GBC-SD gallbladder cancer cell growth inhibition and apoptosis." (PMID 25046749, 2014). "Moreover, metformin can inhibit tumor growth and downregulate HIF-1α and VEGF expressions in gallbladder cancer." (PMID 36046821, 2022). "However, the functions and clinical significance of HIF-1A in gallbladder cancer (GBC) are still controversial, and it has not been studied in normal gallbladder tissues." (PMID 33403040, 2021).
idiopathic pulmonary fibrosis (15 papers, 2017 to 2026). Idiopathic pulmonary fibrosis (IPF) is a nonneoplastic pulmonary disease that is characterized by the formation of scar tissue within the lungs in the absence of any known cause. "And DQ, which targets BCL-2 family members and HIF-1α, PI3-kinase, and p21-related anti-apoptotic pathways, effectively reduces physical impairment in people with idiopathic pulmonary fibrosis (IPF)." (PMID 37211559, 2023). "Moreover, dasatinib plus quercetin (DQ), which not only targets BCL-2 family members, but also HIF-1α, PI3-kinase and p21-related anti-apoptotic pathways, has proved efficient at improving physical dysfunction in idiopathic pulmonary fibrosis (IPF) patients." (PMID 33352064, 2020).
intrauterine growth restriction (15 papers, 2012 to 2025). "Alterations in HIF-1α function are associated with pregnancy complications, including preeclampsia, intrauterine growth restriction (IUGR), and placental insufficiency, underscoring its critical role in fetal-maternal health." (PMID 40136686, 2025). "In research on the pathogenesis of selective intrauterine growth restriction (sIUGR), overexpression of hypoxia-inducible factor (HIF-1α) induces upregulation of SLC38A1, which reduces cell growth and migration." (PMID 39834787, 2024). "GLUT3 in intrauterine growth restriction was colocalized with the hypoxic transcription factor HIF-1α whereas FGF21 has been reported to induce GLUT1 expression in adipocytes." (PMID 25890271, 2015). "They concluded that HIF-1A overexpression induced intrauterine growth restriction." (PMID 40804807, 2025). "Maternal nutrient restriction increased the histone acetylation and hypoxia inducible factor-1α (HIF-1α) binding levels in the ET-1 gene promoter of pulmonary vein endothelial cells (PVECs) in intrauterine growth restriction (IUGR) newborn rats, and continued up to 6 weeks after birth." (PMID 25131455, 2014). "In an experimental study, mice injected with an adenovirus expressing HIF-1A exhibited HIF-1A overexpression in the fetus, which resulted in intrauterine growth restriction, and their placenta was significantly smaller compared to control." (PMID 40804807, 2025). "Fetal growth restriction (FGR) and PE often share a common pathophysiology; however, it is unknown whether increased placental HIF-1α occurs in FGR." (PMID 28423052, 2017). "Both HIF-1a and HIF-2a are highly expressed in the placenta of women with preeclampsia and their overexpression in experimental models has been shown to result in impaired trophoblast differentiation, proteinuria, hypertension and intrauterine growth restriction (IUGR)." (PMID 41226469, 2025).
lung disease (15 papers, 2012 to 2024). "Although hypoxia-inducible factor(HIF) signaling is a mechanism related to disease progression in group 3 PH(associated with lung diseases and/or hypoxia), increased HIF-1α hasalso been observed in the lung tissue of patients with PAH and CTEPH." (PMID 39139420, 2024). "Hypoxemia secondary to lung disease activates hypoxia-inducible factor 1-alpha (HIF-1-α), stimulating tissue fibrosis and activating fibroblasts and ECM deposition." (PMID 37893011, 2023). "It has been shown that HIF-1α activation, a common dysregulated pathway in PH and lung diseases, can inhibit β-oxidation of long-chain fatty acids leading to accumulation of fatty acids." (PMID 36902298, 2023). "Hypoxia-inducible factor-1α (HIF-1α) is a key regulating factor in cell response to hypoxia, which has been found to participate in many lung diseases." (PMID 34194423, 2021). "In the present study, however, expression of HIF-1α and HIF-2α were unaffected in HIF3A gene-disrupted mice compared to the WT mice, suggesting that the lung disorder of HIF3A gene-disrupted mice is not caused by a mechanism mediated by HIF-1α or HIF-2α." (PMID 38717999, 2024). "However, the general protective role for HIF-1α in response to Aspergillus was primarily described in the context of invasive pulmonary disease." (PMID 36275017, 2022). "Moreover, increased HIF-1α levels in SHS-exposed mice lungs points towards a novel mechanism for SHS-induced lung disease initiation in the pediatric population." (PMID 28150141, 2017). "Thus, we designed this preliminary study to identify the effects of CS/SHS on HIF-1α expression, proteostasis/autophagy, and its potential impact on development of pediatric lung disease(s) such as BPD." (PMID 28150141, 2017). "However, C57BL/6 mice were clearly afflicted with more extensive lung disease so this strain might be expected to mount a stronger hypoxic response leading to higher levels of HIF-1α." (PMID 23006927, 2012). "Previous studies have also shown that HIF dysfunction is closely related to inflammatory airway conditions, and HIF1A plays a central role in the development of COPD and other lung diseases." (PMID 35002688, 2021). "HIF-1α stabilization and enhanced VEGF expression followed by prolyl hydroxylase inhibition increased lung angiogenesis in the primate model of bronchopulmonary dysplasia, a chronic form of lung disease." (PMID 25257482, 2014). "Despite the importance of HIF signaling, the role of HIF-1α and HIF-2α in lung diseases has not been established and only a few studies addressed the role of HIFs in primary human immune cells." (PMID 30946009, 2019).
metastatic carcinoma (15 papers, 2010 to 2026). A carcinoma which has spread from the original site of growth to another anatomic site. "During metastasis, the IRE1α-XBP1 pathway interacts with HIF1α (Hypoxia-inducible factor 1-alpha) to promote tumor growth and survival in hypoxia, making it a potential target for treating metastatic cancer." (PMID 41346768, 2026). "In the current landscape of metastatic cancer research, hypoxia-inducible factor 1-alpha (HIF1A) has emerged as a critical player." (PMID 39458948, 2024). "Combining this strategy with existing HIF1α inhibitors and chemotherapies could be an effective anticancer approach for treating aggressive metastatic cancers." (PMID 40701956, 2025). "The clinical development of echinomycin was also discontinued due to the lack of anticancer efficacy in patients with solid tumors, but its incorporation in liposomes has been recently suggested as a safe and effective therapeutic option, profiting from the HIF-1α inhibition in metastatic cancers." (PMID 38667760, 2024). "Furthermore, a positive correlation of the gene expression from two different metastatic cancer data suggesting the involvement of KDM6B in regulating HIF1α, SOX2, and CD44 further indicates the stemness regulatory function of KDM6B in various cancer types." (PMID 35186918, 2022). "Despite abundant data supporting the notion that HIF‐1α can promote every single aspect of the multistep metastatic cascade, only a few clinical studies have addressed HIFα expression in metastatic cancers and its role in disease progression." (PMID 32686360, 2020). "Thus, high HIF-1α protein levels are usually detected in metastatic cancers, whereas comparatively much lower HIF-1α protein is detected in both benign cancers and noncancer cells." (PMID 31600993, 2019). "Authors observed increased HIF-1α staining intensity in higher stage and metastatic cancers." (PMID 29084538, 2017). "The significant contribution of HIF in tumor development is well understood as studies have revealed the overexpression of HIF-1a and HIF-2a in metastatic cancers of humans, and this overexpression corresponds to tumor angiogenesis and mortality rate of patients." (PMID 35686109, 2022).
pheochromocytoma (15 papers, 2005 to 2025). "The regulation of the catecholamine biosynthesis in pheochromocytoma cells seems to be primarily regulated by HIF1α under extrinsic hypoxia." (PMID 31035382, 2019). "Furthermore, a previous article reported that PD‐L2‐positive pheochromocytoma and paraganglioma were characterized by higher HIF‐1α expression." (PMID 34363337, 2021). "No mutations or deletions in the locus containing HIF1A have yet been identified in paragangliomas or pheochromocytomas." (PMID 28187001, 2017). "Increased succinate and expression of HIF1α and angiogenic genes, such as VEGF, as well as high density of microvessels were found in pheochromocytoma tumor tissues." (PMID 37749638, 2023). "Therefore, in addition to the HIF1α-mediated intrinsic hypoxia prominent in both empty vector control and Hif2α-expressing MPC, HIF2α-mediated pseudohypoxia further enhances radioresistance in pheochromocytoma cells by protecting the more radiosensitive outer cell layers." (PMID 33494435, 2021). "For improved understanding of the underlying mechanisms we investigated the impact of hypoxia and pseudohypoxia on catecholamine biosynthesis in pheochromocytoma cells naturally lacking Hif2α (MPC and MTT) or expressing both Hif1α and Hif2α (PC12)." (PMID 31035382, 2019).
type 1 diabetes (15 papers, 2009 to 2025). "Indeed, mice with a beta cell-specific HIF-1α deletion are more susceptible to type 1 diabetes after exposure to coxsackieviruses or beta cell toxin." (PMID 33496820, 2021). "NAC and ALP synergistically attenuate post-ischemic injury and cardiac dysfunction in type 1 diabetic rats and in isolated cultured adult rat cardiomyocytes exposed to high glucose and H/R, an effect associated with enhancement of cardiac HIF-1α/HO-1 signaling in response to MI/R." (PMID 23874823, 2013). "Decreased β-cell HIF1α could contribute to type 1 diabetes pathogenesis by increasing sensitivity to apoptosis, increasing β-cell stress (as HIF1α mediates a protective response to stress), and by increasing the load of improperly folded insulin." (PMID 39769216, 2024). "Taken together, the current experimental data showed that type 1 diabetes impaired myocardial AMPK signaling and AKT/GSK-3β/HIF-1α signaling." (PMID 29088824, 2017).
experimental autoimmune encephalomyelitis (14 papers, 2015 to 2025). An autoimmune demyelinating disease of the central nervous system that is produced experimentally in animals by the injection of homogenized brain or spinal cord in Freund's adjuvant. "Consequently, DAPK deficiency leads to excess HIF-1α accumulation, enhanced IL-17 expression and exacerbated experimental autoimmune encephalomyelitis." (PMID 27312851, 2016). "In both experimental autoimmune encephalomyelitis (EAE) and collagen-induced arthritis (CIA), the differentiation of IL-10+ regulatory B cells is impaired as a result of HIF-1α deficiency." (PMID 39543372, 2025). "Deletion of HIF-1α in Th17 cells leads to delayed development of experimental autoimmune encephalomyelitis (EAE) in a Th17-polarized transfer model of EAE, emphasizing the importance of HIF-1α in the pathogenicity of Th17 cells." (PMID 33120978, 2020). "Mice with B cell-specific deletion of Hif1a have reduced number of IL-10-producing B cells, which result in exacerbated collagen-induced arthritis and experimental autoimmune encephalomyelitis." (PMID 29343683, 2018). "Additional knockout of HIF-1α restores the normal differentiation of Dapk−/− Th17 cells and prevents experimental autoimmune encephalomyelitis development." (PMID 27312851, 2016). "Here we show that similar to MS lesions, HIF-1α is induced mainly in astrocytes and microglia/macrophages in white matter areas in experimental autoimmune encephalomyelitis (EAE), a mouse model for MS." (PMID 26213713, 2015). "Based on this, they developed a synthetic lactate-producing probiotic, which successfully suppressed T cell-driven central nervous system autoimmunity in experimental autoimmune encephalomyelitis (EAE) models through the activation of HIF-1α–NDUFA4L2 signaling in DCs." (PMID 38455045, 2024). "It has recently been demonstrated in experimental autoimmune encephalomyelitis (EAE) that IL-17A recruits IL-1β-secreting myeloid cells that prime pathogenic γδT17 and Th17 cells, whereas mice with HIF-1α-deficient T cells are resistant to induction of Th17-dependent EAE." (PMID 36961533, 2023). "To test this hypothesis, we analyzed the effect of cell-specific genetic ablation or overexpression of HIF-1α on the onset and progression of experimental autoimmune encephalomyelitis (EAE), a mouse model for MS." (PMID 26213713, 2015). "This study aimed to determine if inhibition of the HIF-1 pathway using the HIF-1a antagonist acriflavine (ACF) can reduce clinical progression and rescue the ocular phenotype in an experimental autoimmune encephalomyelitis (EAE) ON model." (PMID 37942317, 2023). "Th17 has high levels of HIF-1α and deletion of HIF-1α in T cells inhibits Th17 differentiation in vitro and in experimental autoimmune encephalomyelitis." (PMID 26824038, 2016). "In an in vivo experimental autoimmune encephalomyelitis (EAE) model, blockade of BCAT1-mediated leucine catabolism, either through a BCAT1 inhibitor or LβhL treatment, mitigated EAE severity by decreasing HIF1α expression and IL-17 production in spinal cord mononuclear cells." (PMID 39085353, 2024).
gastric adenocarcinoma (14 papers, 2009 to 2025). "The findings revealed that the expression of NFKB1 and HIF1A genes was significantly high, and IL-6 expressed the same between the stomach adenocarcinoma tissues compared to normal tissues." (PMID 39816318, 2024). "Another proton pump inhibitor, Pantoprazole, was also shown to downregulate the HIF-1α signaling pathway in human gastric adenocarcinoma cells." (PMID 35563731, 2022). "Results showed that this cotreatment modulated numerous critical proteins, such as EGFR/HER2/HER3, Kras/ERK/Vimentin, and mTOR/HIF1-α/HK2/LDHA pathways of gastric adenocarcinoma AGS cells." (PMID 36145507, 2022). "In agreement with our previous data, the parental strain was able to induce the HIF-1α reporter activity both in human gastric adenocarcinoma AGS and MKN45 cell lines." (PMID 31185594, 2019). "Immunoblot analysis showed that HIF-1α was highly expressed in gastric adenocarcinoma, especially in poorly-differentiated tumors, compared with NGT (P < 0.05)." (PMID 27729869, 2016). "In contrast, two Japanese studies reported lower percentages of HIF-1α-positive tumour cells in human gastric adenocarcinoma samples." (PMID 19223895, 2009). "Given these sharp contrasts, a definite agreement on the expression pattern of HIF-1α in T1 gastric adenocarcinomas cannot be reached at this point and should be clarified by future work." (PMID 19223895, 2009). "Here, we describe for the first time that HIF-1α constitutes a central metastasis-supporting factor in human gastric adenocarcinoma." (PMID 19223895, 2009). "We seek to determine whether and how miR-186/HIF-1α axis could reprogram cellular metabolism and proliferation in gastric adenocarcinoma." (PMID 27159677, 2016). "The results confirmed that HIF-1α was the direct target of miR-186 in gastric adenocarcinoma." (PMID 27159677, 2016). "The study analysed the mRNA expression levels of ALB, BCL-2, NFKB1, HIF1A, and IL-6 in 408 stomach adenocarcinoma samples alongside non-tumour gastric tissues." (PMID 39816318, 2024). "Finally, we performed immunohistochemistry for HIF-1α and ANXA1 on a tissue microarray comprising 397 samples of human gastric adenocarcinoma." (PMID 26760764, 2016). "Several immunhistochemical studies showed that HIF-1α is overexpressed in gastrointestinal stromal tumours of the stomach and gastric adenocarcinomas but absent in normal gastric mucosa." (PMID 19223895, 2009). "Finally, the pre-incubation of the human gastric adenocarcinoma cell line AGS with blocking antibodies against Toll-like receptor-2 (TLR2), but not TLR4, prevented HIF-1α induction." (PMID 31185594, 2019).